TNF (tumor necrosis factor)
Diseases named in the same sentence as TNF in open-access papers (continued):
Sharing a sentence is not in itself a finding about the gene and the disease.
Insulin resistance (continued). "Hepatic macrophages, which consist of resident Kupffer cells and recruited bone marrow-derived macrophages, are the major cells that produce inflammatory mediators such as TNF-α and IL-1β to cause systemic insulin resistance as well as NASH23." (PMID 26603489, 2015). "Prospective studies have shown that GDM is linked to the down-regulation of adiponectin and anti-inflammatory cytokines (e.g., IL-4 and IL-10) and up-regulation of leptin and pro-inflammatory cytokines implicated in insulin resistance (e.g., IL-6 and TNF-α)." (PMID 26110385, 2015). "Actually, PP4 silencing and suppression of PP4 activity ameliorated TNF-α-induced hepatic insulin resistance, whereas over-expression of PP4 caused insulin resistance." (PMID 26666849, 2015). "One prospective study demonstrated an association between TNF-α levels and insulin resistance in the first and second trimesters when adjusted for age, BMI, triglycerides (TG) and other confounders." (PMID 26110385, 2015). "As a feature of insulin resistance, white adipose tissue, viz., visceral fat causes chronic inflammation due to macrophage infiltration and/or the release of TNF-α." (PMID 25679220, 2015). "TNF-α is an adipose tissue-derived proinflammatory cytokine that causes insulin resistance by enhancing adipocyte lipolysis and increasing the serine/threonine phosphorylation of IRS-1 (insulin receptor substrate-1)." (PMID 26136779, 2015). "TNFα treatment caused insulin resistance as indicated by a 44% reduction in insulin-stimulated 2DOG uptake, loss of GLUT4 (−48%), and reduced insulin-regulated AKT phosphorylation (−54%)." (PMID 26240143, 2015). "TNF-α is recognized as a multifunctional cytokine implicated in inflammation, apoptosis and cell survival as well as induction of insulin resistance." (PMID 25887648, 2015). "Previous studies have linked TNFα to insulin resistance in rat and human skeletal muscle, as well as indicated TNFα-mediated effects on substrate utilization." (PMID 24691558, 2015). "Higher intramuscular adipose tissuewas strongly associated with insulin resistance and higher serum inflammatory markers including C-reactive protein, interleukin-6, and tumor necrosis factor-alpha." (PMID 26030144, 2015). "It should be noted that elevated TNF-α levels are also associated with insulin resistance, hypertriglyceridemia, and hepatic steatosis." (PMID 26588700, 2015). "We found that higher levels of CRP, as well as of PAI-1 and TNFα, were independently associated with both insulin resistance and microvascular dysfunction (lower capillary density)." (PMID 26549941, 2015). "Reports IL-6 and TNF-α are the major inflammatory adipokines that impair insulin signaling and its actions that result in the associated development of insulin resistance and type 2 diabetes." (PMID 26170870, 2015). "Chronic elevation of pro-inflammatory cytokines (TNF-α) is implicated in insulin resistance, however the underlying mechanisms in general and specifically the molecular basis of TNF-α mediated GLUT4 repression are unclear." (PMID 26468734, 2015). "TNF-α has been implicated in insulin resistance and liver fibrosis as well as advanced stages of NAFLD in humans." (PMID 25922835, 2015). "BPA plasma levels (ELISA), metabolic risk factors, homeostasis model assessment of insulin resistance index, plasma monocyte chemoattractant protein 1, interleukin-6 (IL-6) and tumor necrosis factor-alpha were performed." (PMID 26021871, 2015). "The adipose tissue can synthesize and release pro-inflammatory cytokines, as TNF-alpha, IL-1 and IL-6, and these inflammatory markers are associated with body fat mass and involved in multiple metabolic pathways relevant to insulin resistance." (PMID 25922592, 2015). "High amounts of TNFα cause an increase in phosphorylation of IRS-1Ser307 leading to insulin resistance and apoptosis." (PMID 25874611, 2015).
Insulin resistance (continued). "The presence of peripheral insulin resistance in other catabolic states has been associated with the overproduction of the proinflammatory cytokines, tumor necrosis factor (TNF)-α or interleukin (IL)-6." (PMID 26426068, 2015). "CD11c is a marker specific to these ATMs that infiltrate adipose tissue in obese individuals and secrete cytokines such as TNF-α and IL-6, both of which are associated with insulin resistance." (PMID 26124830, 2015). "Local TNF-α overexpression caused cardiac insulin resistance while exacerbating functional and structural sequelae of post-MI." (PMID 26659007, 2015). "In metabolic disorders, ER stress has been linked to insulin resistance and pro-inflammatory TNF-α signaling." (PMID 25617315, 2015). "At a cellular level, TNF-dependent activation of stress-related kinases inhibits insulin signaling, causing cellular insulin resistance." (PMID 24563869, 2014). "TNF-α causes insulin resistance and inflammation response, and PAI-1 promotes thrombosis and inflammation." (PMID 24667131, 2014). "Adipose tissue produces large amounts of TNF-α whereas knockout mice deficient on TNF-α or its receptor are protected from developing the insulin resistance." (PMID 25601838, 2014). "Among these proinflammatory cytokines, TNF-α and leptin have been suggested as the strongest predictors of pregnancy-associated insulin resistance." (PMID 25202741, 2014). "Because TNFα is reported to cause insulin resistance in many other tissues, including adipocytes and myeloid progenitor cells, it would be expected that inhibition of TNFα would protect cells and normalize insulin signaling." (PMID 25138272, 2014). "This association is surprising, given that anti-TNF therapy is reported to improve insulin resistance in RA patients." (PMID 25988122, 2014). "We have previously reported that β2KO mice have increased SOCS3 levels and IRTyr960 phosphorylation, which are both associated with increased TNFα levels and insulin resistance." (PMID 25138272, 2014). "Other studies have also revealed that proinflammatory cytokines IL-6 and TNF were among the first to be implicated as a predictor or pathogenic mediator of insulin resistance, CVD, and in patients with type 2 diabetes." (PMID 25309773, 2014). "The high level of circulating TNF-α was primarily considered to be an inflammatory response, which is known to be causally related to insulin resistance and metabolic syndrome state." (PMID 24441717, 2014). "Other studies have shown that TNF-α causes cardiac insulin resistance by inducing degradation of insulin receptor substrate protein 1, which is critical for cardiac insulin signaling." (PMID 24521405, 2014). "In this line, it has been proposed that TNF-α can be one of the mediators for the insulin resistance and endothelial dysfunction associated to type 2 diabetes mellitus." (PMID 25518980, 2014). "Proinflammatory M1 macrophages induce an inflammatory state and insulin resistance through inhibition of insulin signaling caused by IL-6 and TNF-alpha." (PMID 24741627, 2014). "TNF-α is also shown to cause insulin resistance which is suggested to interfere negatively with lipid metabolism." (PMID 27433517, 2014). "TNFα is a pro-inflammatory cytokine that has been implicated in insulin resistance and has been shown to inhibit ADPN production." (PMID 24915004, 2014). "In the present study increased PP was associated with biomarkers of insulin resistance (TNF-α) and systemic inflammation (neutrophil count) in elderly women." (PMID 25105150, 2014). "Inflammatory mediators such as tumor necrosis factor alpha (TNFα) and interleukin-6 (IL-6) are important mediators of catabolic responses such as protein loss and of metabolic disturbances such as insulin resistance." (PMID 25614714, 2014). "In patients with ankylosing spondylitis, TNF-alpha blockade was associated with improvement of insulin resistance, markers of metabolic syndrome, and biomarkers of endothelial dysfunction." (PMID 25177690, 2014).
Insulin resistance (continued). "Leptin, TNF-α, and resistin correlating with body fat mass, has been reported to be associated with insulin resistance and atherosclerosis." (PMID 24684833, 2014). "Since plasma TNF-alpha is associated to insulin resistance, one can assume that this cytokine plays a significant role in the pathogenesis of chronic insulin resistance in humans." (PMID 24991532, 2014). "Adiponectin-deficient mice exhibited insulin resistance along with increased expression of TNFα in adipose tissue." (PMID 23964268, 2013). "TNFα regulates IL-6 synthesis and aromatase expression in the adipose tissue, and it has been implicated in the development of insulin resistance, all potential promoters of breast tumorigenesis." (PMID 23819063, 2013). "Both ROS and TNFα are reported to be able to cause insulin resistance and to be potent activators of JNK—also conceivably a factor contributing to the metabolic syndrome." (PMID 24324517, 2013). "The KEGG Adipocytokine Signaling Pathway describes signaling cascades arising from the adipocytokines that have been implicated in insulin resistance and sensitivity: TNF-alpha, leptin and adiponectin." (PMID 26029481, 2013). "HF IU increased hepatic expression of genes associated with insulin resistance (TNFα, SOCS3, PAI-1) and cellular stress (TXM, MAFF and DUSP)." (PMID 23690974, 2013). "Both TNF-alpha and IL-6 are positively related to adiposity, and correlate with insulin resistance and cardiovascular disease (CVD) risk factors." (PMID 23530957, 2013). "Accordingly, HFD fed SFRP5 deficient mice Sfrp−/− have insulin resistance and fatty liver along with enhanced inflammatory macrophage accumulation to produce IL-6, TNF-α, and CCL2 suggesting that SFRP5 is an anti-inflammatory adipokine." (PMID 23781214, 2013). "TNF-α actively participates in the development of insulin resistance and IL-6 is linked with type II diabetes." (PMID 24302970, 2013). "Primary cytokines involved in insulin resistance-associated inflammation are tumor necrosis factor alpha (TNF-α) and interleukin-6 (IL-6)." (PMID 24101915, 2013). "Excess production of TNF-α and low adiponectin are associated with insulin resistance and nonalcoholic fatty liver." (PMID 23431426, 2013). "Certain sentinel cells, including macrophages and fat cells, secrete tumor necrosis factor (TNF)-α, IL-6 and other inflammatory agents that cause a low-grade inflammatory condition and accordingly trigger insulin resistance, diabetes and related diseases." (PMID 24137239, 2013). "The “classic” adipocytokines such as adiponectin, TNF-α, and IL-6 have been regarded as consistent surrogate markers to reflect cardiovascular risk and other metabolic abnormalities in subjects with insulin resistance." (PMID 23970879, 2013). "Taken together, there is an abundance of support for the conclusion that TNFα levels are associated with insulin resistance, although the mechanism in the retina is less clear." (PMID 23592917, 2013). "Previously, it was shown that chronic exposure to TNF-α decreased insulin receptor phosphorylation in adipocytes and that increased levels of TNF-α, IL-6 and IL-1β are linked to systemic inflammation and accompany insulin resistance." (PMID 23915208, 2013). "TNF-α has been implicated in the progression of insulin resistance; it disrupts phosphorylation of several proteins involved in insulin-signalling pathway, including IRS1, tyrosine, and most importantly, the downregulation of glucose transporter 4 (GLUT4)." (PMID 24391675, 2013). "For instance, GHR knockout mice have reduced levels of pro-inflammatory cytokines implicated in development of insulin resistance (TNF-α and IL-6), possibly as a consequence of anti-inflammatory effects of increased levels of adiponectin in these mutants." (PMID 23483710, 2013). "Several studies in healthy subjects have confirmed that elevated levels of CRP and cytokines IL-6 and TNF-alpha are associated with insulin resistance." (PMID 23690772, 2013).
Insulin resistance (continued). "TNF-alpha is an important inflammatory mediator associated with insulin resistance, and increased TNF-alpha has been linked to gestational diabetes." (PMID 26029481, 2013). "It has been well documented that high expression of TNF-α in adipose tissue is related to insulin resistance, considered to be an important pathogenic mechanism for the development of T2DM." (PMID 23527193, 2013). "Both TNF-α and Il-6, secreted by adipose cells, seem to trouble intracellular signaling, cause insulin resistance, and stimulate hepatic production of phase acute-phase proteins such as CRP." (PMID 23009606, 2012). "Selective constitutive activation of NFκB signaling in hepatocytes produced mild elevations of TNF-α and IL-1β in mouse liver and an association with severe hepatic insulin resistance." (PMID 23118937, 2012). "The present work also verified that aside from C4, TNF-α, and IL-6, inflammatory markers were associated with waist circumference and insulin resistance, emphasizing that this syndrome is proinflammatory." (PMID 21822486, 2012). "Insulin resistance is associated with inflammatory factors such as tumor necrosis factor-α (TNF-α) and interleukin-6 (IL-6) in T2DM patients." (PMID 22548048, 2012). "Along with MCP-1 and F4/80, we observed higher expression levels of proinflammatory cytokines, such as IL-1β, IL-6 and TNFα, which are actively secreted by macrophages or adipocytes and cause insulin resistance." (PMID 22272317, 2012). "Insulin resistance seems to be associated with a predominantly Th1 cytokine pattern: TNF-α (and to a lesser extent IL-1 and IL-6), produced by visceral fat among others, inhibits insulin signaling pathways, leading to insulin resistance." (PMID 23204981, 2012). "Treatment of animals with CL 316,243, a β3-adrenergic agonist, showed an improvement of insulin-resistance that was linked with the suppression of TNF-α mRNA expression in WAT." (PMID 23056223, 2012). "TNF-α was the first pro-inflammatory mediator linked to inflammation, obesity and insulin resistance." (PMID 23201837, 2012). "TNFα can induce hepatic lipogenesis and increase hepatic triglyceride production and TNFα deficiency protected from HF-induced hepatic steatosis and insulin resistance." (PMID 22272317, 2012). "In obese humans are observed increased circulating levels of TNF-α; this event has been proposed to be causatively involved in the evolution of insulin resistance, type 2 diabetes, and its complications." (PMID 22523672, 2012). "We demonstrate an increase in TNF-α release causing upregulation of Map4k4 expression that disrupts the normal metabolic function of adipose tissue and thereby leads to insulin resistance." (PMID 22816003, 2012). "In this regard, higher levels of TNFα and IL-6 have been associated with excess adiposity levels and insulin resistance." (PMID 22768323, 2012). "The authors argued that the increased generation of reactive oxygen species by glycosylation or tumor necrosis factor under diabetic conditions would cause excessive oxidation and cellular stress, and lead to insulin resistance." (PMID 22952896, 2012). "TNF-α is a cytokine expressed by both macrophages and adipocytes and is known to induce insulin resistance associated with hyperinsulinemia by impairment of insulin action on peripheral glucose uptake and hepatic glucose output." (PMID 23056223, 2012). "These M1 macrophages are associated with insulin resistance and are characterized by the expression of markers such as IL-1β, TNFα and CD11c." (PMID 23110196, 2012). "TNF-alpha is expressed in and secreted by adipose tissue in association with the degree of adiposity and insulin resistance." (PMID 22848362, 2012). "Insulin resistance also leads to an increased expression of TNF-α and its dysregulation is associated with the development of steatosis and inflammation within the liver." (PMID 22312273, 2012).
Insulin resistance (continued). "Namely, it is considered that the increased serum levels of lipopolysaccharide and TNF-α associated with P. gingivalis infection induce insulin resistance, leading to the development of type 2 diabetes." (PMID 22340817, 2012). "The underlying mechanism of the insulin resistance-inducing effect of TCDD is stimulation of TNF-α production." (PMID 21556177, 2011). "We found clear evidence that signals for IL-1β, IL1RN, TNF-α and TGFβ-1 are present in both adipose and liver tissues and that these are linked to the development of inflammation and insulin resistance in the HFC-fed mice." (PMID 21410952, 2011). "HCC development was associated with GH and insulin resistance, enhanced tumor necrosis factor alpha (TNF-α) expression, high reactive oxygen species levels, and augmented liver and DNA damage parameters." (PMID 21725989, 2011). "Diabetes in conjunction with LF had decreased levels of TNF-α and IL-6 (cytokines that have already been associated with insulin resistance (IR)), compared to those with DM alone." (PMID 20559443, 2010). "Increased TNFα, leptin, and resistin levels and decreased adiponectin expression in adipose tissues are associated with the development of insulin resistance and vice versa." (PMID 20148112, 2010). "Together these data indicate that increased ileal TNF-α mRNA shows strong positive associations with weight gain, adiposity and subsequent development of insulin resistance induced by HF diet." (PMID 20808947, 2010). "NF-κB causes insulin resistance by stimulating proinflammatory cytokines like TNF-α, IL-6, IL-1β, and resistin, which in turn activates JNK and NF-κB pathways to create a vicious cycle that will exacerbate tissue damage." (PMID 20508722, 2010). "Insulin resistance is associated with increased plasma levels of proinflammatory cytokines such as TNF and IL6, and with interactions between TNF and NFkappaB that lead to an increase of oxidative stress." (PMID 20459604, 2010). "While there are a plethora of genes associated with inflammation and insulin resistance, I will focus on a select few TNF-α, JNK, NF-kappa B which based on the literature are plausible candidates." (PMID 18570670, 2008). "Inflammation caused by cardiac surgery increased insulin resistance in a time dependent manner which was paralleled by an induction of cortisol, TNFα, IL6, resistin and leptin while adiponectin serum levels were decreased." (PMID 19087258, 2008). "TNF alpha represents a potential link between adiposity and insulin resistance, since circulating levels are associated with adipose mass and exogenous administration increases insulin resistance." (PMID 16965635, 2006). "Perhaps this represents a modulating effect as TNF-α stimulates lipolysis but TNF-α levels are associated with hyper insulinaemia and insulin resistance." (PMID 16669999, 2006). "A complicating factor in untangling the cause-effect relationships underlying sarcopenia is the ability of IL-6, TNF-α, physical inactivity, abdominal obesity, and other factors to cause insulin resistance in the elderly." (PMID 15904534, 2005). "PPARγ also negatively regulates transcription of several genes that impair insulin action, including tumor necrosis factor-α (TNFα) and leptin, proinflammatory cytokines produced by adipocytes and associated with insulin resistance." (PMID 15634355, 2005). "One of these is increased expression of tumour necrosis factor (TNF)α, since TNFα is associated with apoptosis of adipocytes but causes insulin resistance." (PMID 15642120, 2005). "In addition, VAT also releases pro‐inflammatory cytokines such as tumour necrosis factor‐alpha (TNF‐α) and interleukin‐6 (IL‐6), both of which are implicated in insulin resistance and endothelial dysfunction." (PMID 41251158, 2026).